TAP1 (transporter 1, ATP binding cassette subfamily B member)
Diseases named in the same sentence as TAP1 in open-access papers (continued):
Sharing a sentence is not in itself a finding about the gene and the disease.
lung carcinoma (15 papers, 1996 to 2025). "In one of the papers, we saw the faulty allele of TAP1 was being associated with its transportation function in lung cancers." (PMID 34047812, 2021). "Previously, we saw that lung cancer caused by impaired human leukocyte antigen (HLA)-1 complex had altered the TAP1 gene." (PMID 34047812, 2021). "Our findings suggest that loss of antigen-presenting molecules (including both MHC class I alleles and TAP-1) is a frequent event in lung cancer." (PMID 8546899, 1996). "The impact of TAP1/2 silencing in lung cancer cells using siRNAs and CRISPR/Cas9 was studied using transcriptomic analysis, phosphoprotein arrays, ATAC-sequencing, measurement of surface HLA-peptide complexes and in vitro tumor-antigen specific T-cell killing." (PMID 40091029, 2025). "In breast, liver, and lung cancer, TAP1 promoter methylation was significantly unchanged for females compared to normal tissue." (PMID 34047812, 2021). "We found under expression of TAP1 for lung cancer in the ONCOMINE analysis, whereas GEPIA2 and GENT2 showed significant overexpression." (PMID 34047812, 2021). "Here the GSE31210 and GSE31210 datasets of lung cancer exhibited that the low expression (n = 180, for both) of TAP1 mRNA exhibited a significantly higher OS in comparison with the higher TAP1 mRNA expressed (n= 24, for both cases) group." (PMID 34047812, 2021). "We therefore evaluated the prevalence of TAP downregulation in human lung cancer specimens by analysing the expression levels of TAP1 and TAP2 mRNA in primary human tumours and autologous normal lungs." (PMID 30504837, 2018). "We found that high levels of the 5 genes, PD-L1, ICAM-1, CXCL10, IRF1, and TAP1, were correlated with better survival probabilities in lung cancer patients treated with immunotherapies (N = 21, p = 0.17 for PD-L1, p = 0.28 for ICAM-1, p = 0.052 for CXCL10, p = 0.023 for IRF1, and p = 0.22 for TAP1)." (PMID 36688994, 2023). "But in our study, we witness the expression of TAP1 to be higher in lung cancer tissues." (PMID 34047812, 2021). "A mechanism for enhancing tumor immunogenicity was investigated by infecting TAP1-deficient mouse lung carcinoma cells with a nonreplicating adenovirus expressing the human TAP1 gene (AdhTAP1)." (PMID 29091951, 2017). "However, we have found that introduction of the B7.1 gene into TAP-negative (TAP−) or TAP1-transfected (TAP1+) murine lung carcinoma CMT.64 cells can augment the capacity of the cells to induce a protective immune response against wild-type tumor cells." (PMID 19629186, 2009). "We demonstrate that curcuphenol induces the expression of the APM components, TAP-1 and MHC-I molecules, in cell lines derived from both metastatic prostate and lung carcinomas." (PMID 37256225, 2023). "We discovered that one of these entities, curcuphenol, induces the expression of the APM components, TAP-1 and MHC-I molecules, in cell lines derived from both metastatic prostate and lung carcinomas." (PMID 37637416, 2023). "Downregulation of TAP1 and/or TAP2 in lung cancer cells, resulting in resistance to TCR-dependent lysis." (PMID 38067336, 2023). "TAP deficiencies have been observed in a wide variety of human cancers, including cervical carcinoma, head and neck carcinoma, melanoma, gastric cancer, and lung cancer, with up to 70% of NSCLC expressing low levels of TAP1 and/or TAP2." (PMID 38067336, 2023). "Our earlier studies have stressed downregulation of TAP1 and/or TAP2 in lung cancer cells, resulting in resistance to TCR-dependent lysis." (PMID 31333652, 2019). "Interestingly, our transcriptomic analysis revealed that TAP1 expression is reduced after TAP2 silencing in lung cancer cells, and TAP2 is also reduced after TAP1 downregulation, supporting interdependency in the expression of these proteins." (PMID 40091029, 2025).
lung carcinoma (continued). "We subsequently focus on the surprising finding that curcuphenol, a component of the culinary spices turmeric and curcumin used in traditional medicines and dietary supplements, induces the expression of APM components, TAP-1 and MHC-I, in both metastatic prostate and lung carcinoma cells." (PMID 37256225, 2023). "Moreover, low TAP1/TAP2 expression led to the overexpression and efficient presentation of the antigen preprocalcitonin in lung carcinoma, as recognized via tumor-specific cytotoxic T lymphocytes." (PMID 35837087, 2022).
colorectal cancer (12 papers, 2019 to 2025). A primary or metastatic malignant neoplasm that affects the colon or rectum. "TAP1 has been reported to be associated with tumor immune escape, and high-expressed TAP1 has been seen as a poor prognostic factor in stage I/II colorectal cancer patients." (PMID 36204659, 2022). "In other malignancies, loss of HLA Class I antigens is often caused by loss of essential molecules of the HLA antigen-processing and presentation system, such as the Transporter Associated with Antigen Processing (TAP1) protein in colorectal cancer and primary cutaneous melanoma." (PMID 31394860, 2019). "In a previous study for colorectal cancer, we saw that there was correlation between TAP1 expression and prognosis in a positive way." (PMID 34047812, 2021). "In colorectal cancer, decreased levels of TAP1 were seen in tumors with perineural invasion, making downregulation of TAP1 a prognostic factor for patients with stage I and II disease." (PMID 32867395, 2020). "Moreover, the downregulation of TAP1 has been reported to elicit immune escape in colorectal cancer." (PMID 35418980, 2022).
esophageal cancer (10 papers, 2012 to 2025). A primary or metastatic malignant neoplasm involving the esophagus. "Loss of TAP1 has been reported to render some tumor cells to escape the immune surveillance and contribute to the clinical course of esophageal cancer." (PMID 31703610, 2019). "Second, down-regulation of HLA-HC and up-regulation of TAP-1 were prognostic factors associated with a poor prognosis in patients with esophageal cancer." (PMID 22134332, 2012). "Furthermore, heterozygote genotype of a gene could influence a susceptibility to an infection, such as that of TAP1 which may decrease a susceptibility to human papilloma virus (HPV) infection but can increases susceptibility to the development of esophageal cancer among the Kazakh populations." (PMID 27449138, 2016). "However, in esophageal cancer, upregulation of TAP1 protein in cancer tissues was found to be an unfavorable prognostic factor." (PMID 32867395, 2020). "Our results showed that TAP1 was upregulated in cervical squamous cell carcinoma (CESC), esophageal carcinoma (ESCA), OC, pancreatic adenocarcinoma (PAAD), acute myeloid leukemia (LAML), etc., indicating the role of TAP1 as a tumor marker across various cancers." (PMID 34957213, 2021). "First, expressions of HLA-HC, β2 microglobulin, and five APM components (tapasin, TAP1/2, LMP7/10) were reduced in esophageal cancer cell lines compared with normal tissue, and their components had different expression levels among the esophageal cancer cell lines on Western blot analysis." (PMID 22134332, 2012).
COVID-19 (8 papers, 2020 to 2024). A disease caused by infection with severe acute respiratory syndrome coronavirus 2. "We observed the distinct association between “severe COVID-19 or rheumatoid arthritis” with JIA that was mediated by a subset of 6p21.3 genes within cluster 8 (AGPAT1, PSMB8, TAP1, HCG4P11, HLA-DMB)." (PMID 39175752, 2024). "In this study, higher APM component expression including TAP1 was found in in vitro models of ACE2high cells and in in silico COVID-19 datasets." (PMID 39625479, 2024). "We observed that genes encoding HLA class 1 (HLA-E, PSMA-6, TAP1, IFI30) were enriched in COVID-19 ECs." (PMID 37029220, 2023). "Specifically, along with CD68, the immunoproteasome-related genes PSMB8, TAP1, PSMB9, PSMB10, and calreticulin (CALR) were all found to be expressed in the CD14+/CD16+ subpopulation of cells during mild COVID-19." (PMID 34225749, 2021).
cutaneous melanoma (8 papers, 2019 to 2023). A primary melanoma arising from atypical melanocytes in the skin. "High expression levels of major APM components including TAP1 and HLA class I loci were directly associated with a better outcome for most cancer patients, including skin cutaneous melanoma, with the exception of brain tumors, uveal melanoma and thymoma." (PMID 32825219, 2020). "As already shown by our group and others, a decreased expression of several HLA class I APM components, such as TAP1, HLA-A, HLA-B and HLA-C, has been associated with poor patient survival in several types of cancer, including cutaneous melanoma." (PMID 32825219, 2020). "Loss of TAP1 expression in cutaneous melanoma is associated with an increase in regulatory T (Treg) cells and neutrophils in cancer, which might alter the immune microenvironment and be involved in reversing resistance to PD1 therapy." (PMID 36774490, 2023). "Increased YAP1 was associated with lower expression of CD8, HLA class I molecules, and TAP1 in cutaneous melanoma tissue, similarly pointing toward decreased immune recognition." (PMID 33798262, 2021). "In cutaneous melanoma, TAP1 was the target of regulation by miRs." (PMID 34439175, 2021). "In addition, our results showed that TAP1 was associated with DSS, PFS, OS in different kinds of tumors such as brain lower grade glioma (LGG), skin cutaneous melanoma (SKCM), and bladder urothelial carcinoma (BLCA)." (PMID 34957213, 2021). "IRF1, PSMB9, TAP1, ETV7, and PSMB10 were related to CD8+ T cell infiltration proportion in thyroid carcinoma, breast invasive carcinoma, head and neck squamous cell carcinoma, hepatocellular carcinoma, lung adenocarcinoma, and skin cutaneous melanoma." (PMID 33330025, 2020).
psoriasis (8 papers, 2018 to 2025). An autoimmune condition characterized by red, well-delineated plaques with silvery scales that are usually on the extensor surfaces and scalp. "A number of studies have pointed out that TAP1 gene polymorphisms are associated with autoimmune diseases such as ankylosing spondylitis and psoriasis." (PMID 41425573, 2025). "Certain SNPs in genes like IL23R, FBXL19, CTLA4, SLC12A8, TAP1, and others predispose individuals to paradoxical psoriasis." (PMID 39000125, 2024). "A previous study from our laboratory found five SNPs (rs11209026 in IL23R, rs10782001 in FBXL19, rs3087243 in CTLA4, rs651630 in SLC12A8, and rs1800453 in TAP1) associated with anti-TNF-induced paradoxical psoriasis reactions." (PMID 36143237, 2022).
glioma (7 papers, 2017 to 2024). A benign or malignant brain and spinal cord tumor that arises from glial cells (astrocytes, oligodendrocytes, ependymal cells). "They showed that HMME-PDT enables glioma cells to recover both the expression of functional TAP1 and the presentation of MHC class I surface antigens." (PMID 39201395, 2024). "The mRNA expression of CANX, HSPA1B, PSMC6, and TAP1 was high in gliomas, whereas that of KLRC2 was low." (PMID 32351547, 2020). "TAP1 is involved in tumor immunity and is abnormally expressed in many types of cancer, including glioma, which may be less immunogenic due to low levels of TAP1 expression." (PMID 39201395, 2024). "We explored the regulation of SAHA on constitutive expression of MHC-I, TAP1, TAP2, LMP2 and LMP7 proteins in glioma cells." (PMID 31737100, 2019).
colon adenocarcinoma (6 papers, 2018 to 2025). "The expression of the ABCB2 (TAP1) gene was upregulated in all four clinical stages, which confirms the analysis where TAP1 exhibited a state of elevated expression in colon adenocarcinoma, too." (PMID 41465541, 2025). "Moreover, among 19 Hub-MHCsig, HLA-DMA, HLA-DMB, and HLA-DOA were positively correlated with microsatellite instability in colon adenocarcinoma, while TAP2, TAP1, and HLA-F were negatively correlated with microsatellite instability in testicular germ cell tumors." (PMID 38714579, 2024). "In accordance with expectations, in most of these cancers (BLCA, BRCA, CESC, colon adenocarcinoma (COAD), HNSC, KIRC, LIHC, OV, SKCM, and STAD, but not READ or UCS) TAP1 levels were significantly correlated with lymphocyte infiltration." (PMID 36759763, 2023).
colon cancer (6 papers, 2012 to 2024). "It has been reported that TAP1 polymorphism increases susceptibility in both genders to colon cancers." (PMID 38046711, 2023). "It has been reported that TAP1 polymorphism has increased susceptibility in both genders in colon cancers." (PMID 38046481, 2023). "Out of the 8 colon cancer cell lines that we investigated, all 8 showed significant downregulation of TAP1 compared to normal colon cells." (PMID 28622390, 2017).
hepatocellular carcinoma (6 papers, 2020 to 2022). A malignant tumor that arises from hepatocytes. "Both GLI1/2 and TAP1 protein levels were significantly elevated in poorly differentiated hepatoma cells." (PMID 32108992, 2020). "Activation of GLI target genes, such as ABCC1 and TAP1, is responsible for drug resistance in hepatoma cells, with a CD133−/EpCAM− surface molecular profile, and GLI1 and truncated GLI1 account for the metastatic feature of the hepatoma cells, with upregulation of matrix metalloproteinases." (PMID 33440657, 2021). "Suppressing GLI1 or TAP1 gene expression ameliorates drug resistance in hepatoma cells." (PMID 32108992, 2020). "In this study, TAP1 was up‐regulated at mRNA and protein levels in both Huh‐7‐trans and Huh‐7‐DN cells and its expression was confirmed to be higher in two subpopulations than other hepatoma cell lines." (PMID 32108992, 2020). "Therefore, the aim of the present study was to elucidate the underlying mechanism of the hedgehog signalling in governing chemosensitivity through modulating TAP1 expression in both Huh‐7‐trans and Huh‐7‐DN subpopulations, the representatives of poorly differentiated hepatoma cells." (PMID 32108992, 2020). "Previous studies have demonstrated that Hedgehog signaling enhances drug resistance by regulating the expression of TAP1 in PDAC and hepatocellular carcinoma." (PMID 35806187, 2022). "ABCB1 and ABCG2 were mainly expressed in well-differentiated hepatoma cells, whereas poorly differentiated hepatoma cells expressed ABCC1 and ABCB2 (TAP1), accompanied by aberrant activation of the Hh signaling." (PMID 33440657, 2021). "TAP1 and GLI1/2 gene expression was assessed in both poorly differentiated hepatoma cells and HCC specimens." (PMID 32108992, 2020).
lung adenocarcinoma (6 papers, 2017 to 2025). A carcinoma that arises from the lung and is characterized by the presence of malignant glandular epithelial cells. "Our study demonstrates an overall reduction in HLA class I-presented immunopeptidome and downregulation of antigen presentation core complex (e.g., TAP1 and ERAP1/2) and immunoproteasome in osimertinib resistant lung adenocarcinoma cells." (PMID 34638461, 2021). "The results indicated that the expression TAP1 was positively related to TMB in CESC, breast invasive carcinoma (BRCA), COAD, lung adenocarcinoma (LUAD), PAAD, sarcoma (SARC), SKCM, and STAD, whereas the highest score was observed for the correlation of TAP1 and COAD." (PMID 34957213, 2021). "No consistent associations between TAP1 or TAP2 downregulation and age, gender, disease stage or smoking status were identified, and the frequency of cancer cell TAP1 and/or TAP2 downregulation was comparable across lung adenocarcinomas harboring activating mutations in EGFR or KRAS." (PMID 40091029, 2025).
autoimmune disease (5 papers, 2017 to 2025). A disorder resulting from loss of function or tissue destruction of an organ or multiple organs, arising from humoral or cellular immune responses of the individual to their own tissue constituents. "ERAP2 is reported to be associated with several other autoimmune diseases and is, as the TAP1 and TAP2 proteins, crucial for proper folding and assembly of the MHC-I heavy chain." (PMID 40883722, 2025). "Major histocompatibility complex (MHC) class-II linked genes proteasome subunit beta 8 (PSMB8) and transporter associated with antigen processing 1 (TAP1), involved in antigen processing and presentation have been reported to be associated with several autoimmune diseases including vitiligo." (PMID 28700671, 2017). "Genes within MHC class II loci along with genes involved in antigen processing and presentation i.e., proteasome subunit beta 8 (PSMB8) and transporter associated with antigen processing 1 (TAP1) have been reported to be associated with several autoimmune diseases including vitiligo." (PMID 28700671, 2017). "TAP1 and TAP2 are antigen presenting transporters and alterations in these genes associate with autoimmune diseases, susceptibility to infections, or malignancies." (PMID 33334016, 2020).
diffuse large B-cell lymphoma (5 papers, 2019 to 2026). "In general, TAP1 alteration frequencies in the pan-cancer cohort fluctuated between 2 and 4%; however, diffuse large B-cell lymphoma (DLBC) exhibited the highest frequency, at > 8%." (PMID 36759763, 2023). "In addition, TAP1 negatively correlated with MSI in OC, MESO, lung squamous cell carcinoma (LUSC), LUAD, diffuse large B-cell lymphoma (DLBC), and TGCT, while the correlation in TGCT had the strongest score." (PMID 34957213, 2021).
gastric cancer (5 papers, 2022 to 2025). A primary or metastatic malignant neoplasm involving the stomach. "Then, we chose three genes (CXCR4, TNFSF18, and TAP1) that were all linked to the length of survival for patients with stomach cancer." (PMID 35509844, 2022). "TAP1 and TAP2 expressions were also higher in EBV-associated gastric carcinoma samples than in normal control tissues or other gastric carcinoma subtypes." (PMID 36619767, 2022). "Finally, we used the eight immunoregulatory genes coexpressed with PDGFD in gastric cancer and the TCGA dataset to create an immune-associated signature made up of two genes (CXCR4 and TAP1)." (PMID 35509844, 2022).
glioblastoma (5 papers, 2022 to 2025). The most malignant astrocytic tumor (WHO grade IV). "Western blot assay indicated that TAP1 is upregulated in glioblastoma compared with adjacent normal brain tissues." (PMID 36759763, 2023). "Selective antigenic silencing is most evident in glioblastoma (GBM) hypermethylation or Polycomb occupancy at CIITA, NLRC5, TAP1/2, and HLA-A/B loci downregulates MHC-I/II expression without altering other immune programs." (PMID 41341594, 2025).
MHC class I deficiency (5 papers, 2014 to 2025). "Mutations in TAP1 result in immune-related diseases such as MHC class I deficiency but are also associated with cardiometabolic diseases, such as type 2 diabetes." (PMID 29740313, 2018). "Autosomal recessive mutations in TAP1, TAP2, TAPBP, or B2M, are associated with major histocompatibility complex (MHC) class I deficiency." (PMID 41298860, 2025). "One disease, Bare lymphocyte syndrome type I, has a full intersection with the TAP complex, because three proteins (TAP1, TAP2 and TAPBP) are the proteins causing the disease and the members of the PC at the same time." (PMID 32591566, 2020). "Indeed, one participant had a CNV spanning three recessive immune genes PSMB8, TAP1, and TAP2, which are associated with autoinflammation, lipodystrophy, dermatosis syndrome (PSMB8), and type I bare lymphocyte syndrome (TAP1 and TAP2)." (PMID 24672537, 2014).